MMP2 (matrix metallopeptidase 2)
Diseases named in the same sentence as MMP2 in open-access papers (continued):
Sharing a sentence is not in itself a finding about the gene and the disease.
glioma (continued). "Chlorotoxin can specifically bind to matrix metalloproteinase 2 (MMP-2), which are overexpressed in the glioma." (PMID 30670934, 2018). "Mechanistically, we first discovered that HMGA2, together with GCN5, facilitated the invasion of glioma cells via inducing chromatin conformational remodeling of the MMP2 gene promoter and epigenetically activating MMP2 gene transcription." (PMID 29733521, 2018). "The binding specificity of this construct was demonstrated in vitro on a C6 cancer cell line and in vivo on an MMP2-overexpressing glioma mouse model." (PMID 30486274, 2018). "Kaplan‐Meier analyses further confirmed that high MMP2 levels indicated a shorter survival time in our glioma and GBM patients." (PMID 29733521, 2018). "We randomly selected four additional genes (AKT2, AKT3 GRB2 and MMP2) from the “glioma” pathway, other than the validated targets of the key miRNAs.to check for downstream effect of miRNA overexpression." (PMID 29769662, 2018). "CTX can decrease the surface expression of MMP-2 and also inhibit its activity, thereby reducing overall invasion ability of glioma cells through compact extracellular spaces in normal brain tissue." (PMID 30486274, 2018). "Using the same assay, Wild-Bode’s group showed that sub-lethal irradiation of glioma cells induces an increase in the migration distances due to an enhanced expression and activation of MMP-2, MMP-9 and MT1-MMP." (PMID 29300332, 2018). "Giusti et colleagues showed, for example, which vesicles produced by glioma cells contain the MMP-2 gelatinase, both in pro-enzimatic and active form, as well as pro-MMP9." (PMID 29261132, 2017). "We found that FoxR2 promotes invasion and migration of glioma cells by increasing the expression and activity of MMP-2." (PMID 28915588, 2017). "We then examined tumor cell invasiveness by a matrigel invasion assay that was used to show MMP2-dependent invasion of glioma cell line U251." (PMID 29113349, 2017). "MMP-9 and MMP-2 degrade the extracellular matrix and result in the migration of glioma cells to other normal tissue area." (PMID 29062841, 2017). "Further, the protein expression of hepatocyte growth factor (HGF), the ligand for c-MET, was found to positively correlate and be co-expressed with MMP-2 in human glioma." (PMID 28234925, 2017). "Lastly, there was only one study that reported the data about MMP-2 expression and the OS and only two studies analyzed the association between MMP-2/TIMP-2 and the grade of gliomas." (PMID 26729052, 2017). "Many evidences show that PLD has a role in cell migration which is key to cell invasion and metastasis and active PLD enhances lymphoma cell metastasis, where as the inactivation of PLD inhibited the metastasis, MMP-2 expression in glioma cell invasion." (PMID 29221154, 2017). "Cross talk between astrocytes and glioma cells results in the activation of astrocyte-derived MMP2 and subsequent glioma migration." (PMID 28670569, 2017). "In sum, CTX, CTX-based peptide derivatives, and CTX-modified delivery systems potentially target both gliomas and non-glioma tumors that overexpress MMP-2." (PMID 30873475, 2017). "In our previous study of radiation effects on glioma cells, we found that the extracellular level of MMP2 was upregulated by radiation." (PMID 29113349, 2017). "Our data confirm that CBX7 inhibits EMT and invasion in glioma, which is manifested by influencing the expression of MMP2, MMP9, E-cadherin, N-cadherin and Vimentin in LN229, T98G cells and primary glioma cells (PGC)." (PMID 28388562, 2017). "In a pathway mediated by the urokinase-type plasminogen activator-plasmin cascade, glioma-derived plasmin activates astrocyte-secreted MMP2." (PMID 28670569, 2017). "Due to the limited number of studies included, the findings about the impact of MMP-2 expression or MMP-2/TIMP-2 on the prognosis of gliomas should be interpreted with caution." (PMID 26729052, 2017).
glioma (continued). "In glioma, MMP-2 is believed to be widely involved in tumor spreading, and previous studies have shown a correlation between MMP-2 and gliomas." (PMID 28234925, 2017). "We provided evidence that FoxR2 promotes glioma cell proliferation, migration and invasion through regulating the expression of p27 and MMP-2." (PMID 28915588, 2017). "MMP2 is a critical enzyme for the degradation of the extracellular matrix and thus contributes to glioma cell migration and invasion." (PMID 28600528, 2017). "In its active form, MMP2 amplifies the glioma-brain macrophage interaction network and potentiates glioma growth and invasiveness." (PMID 29410971, 2017). "MMP2, the key matrix metallopeptidase gene overexpressed in high grade glioma functions in promoting glioma cell invasion." (PMID 29113349, 2017). "Glioma cells secrete an array of proteases to be involved in glioma cell invasion, including MMP2 and MMP9, and the membrane-bound MMP, MT1-MMP (also known as MMP-14)." (PMID 29207533, 2017). "In this study, our results demonstrate that FoxR2 contributes to glioma cell proliferation, migration and invasion by regulating the expression of p27 and MMP-2." (PMID 28915588, 2017). "In glioma cells, MMP-2 and MMP-9 are highly expressed and are involved in GBM migration and invasion." (PMID 29062841, 2017). "Visual inspection of the funnel plot revealed asymmetry in analysis of the association between MMP-2 or TIMP-2 expression and glioma grade, indicating the possibility of publication bias." (PMID 26729052, 2017). "It has been reported that hypoxia induced glioma cell migration by increasing the activity and protein level of MMP-2." (PMID 29156717, 2017). "Id4 has been shown to inhibit glioma invasion in vitro by inhibiting MMP2 expression via an inhibitory interaction with Twist1, a class II bHLH transcription factor that is highly expressed in GBM and is crucial for MMP2 expression." (PMID 28122577, 2017). "Taken together, our results indicated that cytomembrane MMP14 was induced by IL-6 secreted from astrocytes, thereby enhancing the migration and invasion of glioma cells through activation of MMP2." (PMID 27613828, 2016). "Decreases in Akt1 levels mediate EMT and effect cell cycle by regulating proteins such as Foxo1, MMP2, p27Kip1 and p21Cip1 in cervical carcinoma and glioma." (PMID 27323412, 2016). "In human glioma, overexpression of Sp1 was demonstrated to increase the invasiveness of glioma cells via increased activity and expression of MMP-2, and was positively correlated with WHO grades of glioma." (PMID 27829234, 2016). "Unlike the other scorpion toxins, chlorotoxin does not bind to a chloride channel directly; instead, it binds with MMP2 and has been explored as a primary receptor site for chlorotoxin on the surface of glioma cells." (PMID 26848686, 2016). "Chlorotoxin selectively binds gliomas and other tumours of neuroectodermal origin via a surface-bound complex, which includes MMP2." (PMID 26848686, 2016). "IL-6 has been reported to enhance tumor (including gliomas) migration and invasion through up-regulation or activation of MMP2 or MMP9." (PMID 27613828, 2016). "Taken together, these results indicated that the activity of MMP2 was increased in glioma cells in co-culture." (PMID 27613828, 2016). "We recently reported the association between the baseline circulating MMP2 level and, to a lesser extent, the MMP9 level, and the response rate, PFS and OS of patients treated with bevacizumab for recurrent high-grade glioma." (PMID 26921265, 2016). "We detected the expression of MMP-2 to evaluate the effect of saw palmetto on the metastasis of glioma." (PMID 26788112, 2015). "Overexpression of SP1 is found to facilitate MMP-2-mediated cell invasiveness and predicts poor clinical outcome of glioma patients." (PMID 26177288, 2015). "Excess matrix metalloprotease MMP-2 expression is therefore related to the easiness of the tissue invasion capability of glioma cells." (PMID 25826056, 2015).
glioma (continued). "Chlorotoxin (CTX), which can preferentially bind to matrix metalloproteinase-2 (MMP-2) in glioma cells, has been developed as an optical imaging contrast agent (CTX: Cy5.5) by conjugation to the fluorescent marker Cy5.5." (PMID 26398657, 2015). "Another important factor in glioma invasion is matrix metalloproteinase 2 (MMP2), which has been reported to destroy local tissue and enhance tumor angiogenesis, thereby accelerating glioma invasion and migration." (PMID 25872784, 2015). "Deb and colleagues show that the lower molecular weight, gelatin-degrading activity is an activated form of MMP-2 in U87 human glioma cells." (PMID 25774514, 2015). "In this study we adopted immunohistochemistry assay to detect CD34, MMP-2, and other indicators in glioma tissue." (PMID 26788112, 2015). "In recent years, a scorpion-derived polypeptide chlorotoxin (CTX) was found to selectively bind malignant gliomas mediated by the cell surface matrix metalloproteinase-2 (MMP-2) and annexin-2, whose expression is increased in gliomas." (PMID 25663909, 2015). "Recent studies have also confirmed that the synthesis and activation of MMP-2 can be induced by glioma." (PMID 26788112, 2015). "In this study, we found that the ATF3 protein and mRNA levels in the human glioma tissues positively correlated with the expression of MMP2, and their expression was increased with the increasing pathological grade of the glioma." (PMID 25872784, 2015). "Bevacizumab can lead to increased regions of hypoxia, a more invasive, treatment-resistant glioma phenotype and enhanced MMP-2 activation." (PMID 26083629, 2015). "Some results suggest that downregulation of AEG-1 significantly inhibits the expression of MMP-2, 7 and 9 in glioma and lung cancer." (PMID 25987128, 2015). "The results of our study demonstrated that the protein expression of MMP2 in glioma tissues was substantially higher than that in normal brain tissues, and the expression of MMP2 was also high in the U373MG cells." (PMID 25872784, 2015). "The results obtained after performing matrigel invasion assays indicate that MMP2 is necessary for glioma cell invasion, and that the WNK2 presence is sufficient to suppress the invasive phenotype." (PMID 25596741, 2015). "Spearman’s rank correlation analysis revealed that the protein expression of ATF3 and MMP2 positively correlated with the pathological grade of the glioma (ρ=0.735, P<0.01; ρ =0.446, P<0.01, respectively)." (PMID 25872784, 2015). "The protein expression of ATF3 and MMP2 in the glioma tissues was evidently higher than that in the normal brain tissues (P>0.05)." (PMID 25872784, 2015). "Accordingly, very recently was demonstrated that SERPINE2 gene knockdown increased MMP-9 and MMP-2 expression in C6 glioma cell line." (PMID 26305372, 2015). "In the glioma tissues of grade II to IV, the expression levels of MMP2 were 1.72±0.29, 4.15±0.45 and 5.82±0.53, respectively, significantly higher compared to those in the normal brain tissues (P<0.05)." (PMID 25872784, 2015). "Glioma-cell invasiveness was often positively correlated with up-regulation of MMP2 or increase of MMP2 activation." (PMID 26307682, 2015). "In our results, LBH589 significantly blocked migration, invasion, and vasculogenic mimicry formation through the down-regulation of VEGF, MMP-2, EphA2 and up-regulation of E-cadherin in U251 glioma cells." (PMID 24418474, 2014). "Penta-acetyl geniposide has been shown to exhibit an inhibitory effect on the abilities of adhesion and motility in C6 glioma cells, decreased the expression of MMP-2 and inhibited the expression of PI3K protein." (PMID 25202424, 2014). "MMP-2 activates several key molecules leading to rapid cell proliferation, increased motility, invasion, and angiogenesis of gliomas." (PMID 24715095, 2014). "The invasive biomarkers of gliomas, MMP-2 and MMP-9, have also markedly positive correlation with TGFB1I1." (PMID 25333259, 2014).
glioma (continued). "For instance, SAA is able to induce the production of MMP-2 and MMP-3 in synovial fibroblasts, MMP-9 activity in monocytic cells and MMP-2 and 9 activity in glioma cell lines." (PMID 24614130, 2014). "In both models, the ability of rSmVAL9 to differentially regulate host cell MMP expression was specifically explored due to the capacity of RTVP-1 to induce the up-regulation and secretion of MMP2 from glioma cells." (PMID 24859313, 2014). "VEGF and MMP-2 and -9 levels in conditioned media from cultures of glioma cells treated with varying doses of X-ray or carbon ion radiation were evaluated by ELISA." (PMID 24893038, 2014). "The expression of the MMP-2 gene in human glioma tissues was found to be upregulated in comparison to normal brain tissue, and dramatically increased in glioblastomas." (PMID 24023566, 2013). "In this case, ERK1/2 activation was shown to increase tumor cell invasiveness in vitro via induction of MMP2 expression, as was seen in astrocyte-glioma co-culture models." (PMID 23596394, 2013). "Matrix metalloproteinases (MMPs) have been proposed to play a key role in mediating glioma invasion through the parenchyma, and peri-tumoral reactive astrocytes have been shown, immunohistochemically, to express MMP2 in post-mortem samples." (PMID 23596394, 2013). "Expression of several candidate genes, such αvβ3 integrin and the matrix metalloproteinases, MMP-2, and MMP-9, in tumor cells has been reported to be associated with radiation-induced glioma cell invasion." (PMID 23940516, 2013). "It not only induces apoptosis in T cells thereby leading to local immunosuppression, but blockade of Fas signaling resulted in impaired MMP-2 activity with a subsequent reduction of glioma invasiveness and motility." (PMID 24023566, 2013). "In fact, anti-MMP-2 siRNA-treated glioma cells underwent apoptosis and MMP-2 inhibition autophagy-associated cell death." (PMID 24023566, 2013). "Artemether reduces the migration and invasion capability of glioma cells and promotes the apoptosis of U87 human glioma cells by inhibiting MMP-2, MMP-9 and p-Akt expressions." (PMID 23593320, 2013). "rSAA increased the mRNA expression of MMP-2 and -9 in gliomas while it presented a dual effect on the activity of these enzymes." (PMID 23533307, 2013). "Our previous study suggests that the infiltrative behavior and the survival mechanisms of glioma have a definite relationship to MMP-2 expression and IR exposure." (PMID 23381805, 2013). "On the other hand, DHMEQ treatment was able to reduce in dose-dependent manner the expression of the metastasis-promoting genes MMP-2, MMP-14, TIMP-2, and uPA, all of which have been implicated in the regulation of invasion in glioma cells." (PMID 23533755, 2013). "In our previous study, we found that RUNX3, being a downstream molecule of TGF-β, inhibited glioma cell invasion and migration by regulating the MMP-2 protein expression and enzyme activity." (PMID 23457532, 2013). "The GAM MT1-MMP expression then in turn activates glioma-derived pro-MMP-2 that subsequently promotes glioma invasion." (PMID 23983766, 2013). "The expression of MMP-2, -9, and -14 in microglia/macrophages was also shown to be enhanced by glioma-derived CX3CL1 (Chemokine (C-X3-C Motif) Ligand) and is significantly associated with the recruitment of microglia into the tumor." (PMID 24023566, 2013). "An angiogenic regulator, angiopoietin 2, induces invasion by stimulating MMP-2 expression and secretion in glioma cells." (PMID 23304519, 2012). "Ectopic expression of TIMP3 inhibited U251 and LN229 glioma cell invasion through the inhibition of MMP2 and MMP9 expression and activity." (PMID 22681957, 2012). "Glioma cells are considered to require the activation of matrix metalloproteinase (MMP)-2, which degrades the extracellular matrix (ECM) during invasion and migration." (PMID 23304519, 2012).
glioma (continued). "Noncanonical Wnt-5a, which signals through β-catenin independent pathways (including the planar cell polarity and the calcium pathways), enhances the migration of glioma cells by regulating the expression of MMP-2." (PMID 22400111, 2012). "On the other hand, enhanced expression of the Fz antagonist sFRP2 reduced glioma invasion by decreasing β-catenin tyrosine phosphorylation and downregulating matrix metalloprotease-2 (MMP-2)." (PMID 22400111, 2012). "Several experiments have used CTX to target brain tumors, exploiting its binding affinity to the glioma-specific chloride ion channel complex, MMP-2, and other proteins." (PMID 23304519, 2012). "We recently reported that PLD enhances expression of the MMP-2 gene by increasing the DNA binding activity of NFκB and Sp1, and then promotes glioma cell invasion." (PMID 20711340, 2010). "The culture supernatants of glioma cell lines were assayed for MMP-2 and MMP-9 gelatinase activities." (PMID 20587068, 2010). "Selective gene suppression of MMP-2 or MMP-9 dramatically reduces the invasive phenotype of gliomas." (PMID 20587068, 2010). "The matrix-metalloproteinases (MMP)-2 and 9 are major factors for this event in brain tumor angiogenesis and MMP-2 and MMP-9 expression is associated with a poor outcome in glioma patients." (PMID 20414333, 2010). "In a recent study, PRL-3 expression level was found to be positively correlated with MMP2 activity in high grade of glioma tissues, supporting our findings about MMP2 activation in LoVo cells." (PMID 19930715, 2009). "A significant decrease in the activity of MMP-2 was observed after 24 h exposure to As2O3 and berberine, likely explaining why co-treatment with berberine and As2O3 strongly affects glioma cell migration and invasiveness." (PMID 18294404, 2008). "In vitro irradiation of human glioma cells increased the expression of MMP-2 and enhanced their invasiveness." (PMID 17987037, 2007). "Interestingly, TIMP-2 demonstrates a dual role: at lower concentrations, it facilitates MMP-2 activation by acting as a bridge between MT1-MMP and pro-MMP-2; however, at higher concentrations, it inhibits MMP-2 activity, thereby reducing glioma invasiveness." (PMID 40265458, 2025). "CLTX binds to chloride channels and MMP2 of malignant glioma cells, inhibiting glioma cell occurrence without causing cytotoxicity." (PMID 40620486, 2025). "Similarly, the MMP-2 concentration was significantly lower in grade II gliomas compared to the healthy controls." (PMID 40512281, 2025). "In addition, in in vitro human glioma cell line experiments, IL-33 stimulated the secretion of matrix metallopeptidase 2 (MMP-2) and MMP-9 through the ST2-NF-κB pathway, thereby increasing the migration and invasion of tumor cells." (PMID 39925809, 2025). "MMP-2 and MMP-9 have also been closely associated with glioma progression and malignancy." (PMID 39941886, 2025). "Notably, MMP-2 and MMP-9 have been associated with glioma invasiveness, while other MMPs, such as MMP-1 and MMP-7, are linked to metastatic gliomas." (PMID 40265458, 2025). "On the other hand, the increase in the MMP-2 protein concentration in advanced gliomas was interpreted as supporting the role of this protein in malignant progression, and a tendency toward shorter survival was shown with higher MMP-2 protein levels in patient serum." (PMID 40512281, 2025). "Elevated expression of MMP2/9 indicates poor prognosis in glioma recurrence." (PMID 40759869, 2025). "IGFBP2 has been shown to increase glioma angiogenesis by upregulating MMP2 expression." (PMID 39903772, 2025). "Sixty glioma-associated targets were associated with CHR, such as MDR transporters (ABCB1, ABCC1, ABCG2), cyclin-dependent kinases (CDK1, CDK6), matrix metalloproteinases (MMP2, MMP9, MMP12), and genes related to inflammation or oxidative stress (NOS2, NOX4)." (PMID 40963691, 2025).